SLAMF8 (SLAM family member 8)
Diseases named in the same sentence as SLAMF8 in open-access papers (continued):
Sharing a sentence is not in itself a finding about the gene and the disease.
tumor (10 papers, 2018 to 2025). "It has been observed that SLAMF8 is largely expressed on tumor-associated macrophages in gastrointestinal cancer, contributing to the tumor’s immunosuppressive microenvironment." (PMID 41162970, 2025). "Recent studies pinpoint the predominant expression of SLAMF8 in tumor-associated macrophages (TAMs), which play a pivotal role in fostering an immune-suppressive tumor milieu." (PMID 37835502, 2023). "Tumor purity and immune cell infiltration, and their correlation with SLAMF8 overexpression, were analyzed and confirmed in PCa samples." (PMID 41162970, 2025). "SLAMF8 expression in PCa tumors negatively correlates with tumor purity but positively correlates with the infiltration of B cells, T cells, dendritic cells, and macrophages." (PMID 41162970, 2025). "Allograft models in C57BL/6 mice were used to study the effects of SLAMF8 overexpression on tumor growth and immune cell infiltration." (PMID 41162970, 2025). "Our study revealed that SLAMF8 is expressed in PCa tumor cells, with its overexpression supporting tumor expansion." (PMID 41162970, 2025). "Significant correlations were observed between SLAMF8 levels and pan-cancer tumorigenesis, tumor metabolism, and immunity." (PMID 38787377, 2024). "Despite its potential significance, more research is needed on the role of SLAMF8 within the tumor microenvironment." (PMID 37835502, 2023). "Compared to non-tumor tissues, SLAMF8 was overexpressed in PCa tumors." (PMID 41162970, 2025). "Furthermore, SLAMF8 expression is positively correlated with immune cell infiltration and tumor metastasis in PCa patients." (PMID 41162970, 2025). "We observed that SLAMF8 overexpression promoted tumor growth significantly." (PMID 41162970, 2025). "This association suggests that SLAMF8, like other SLAM family members, may influence the tumor’s immune milieu." (PMID 37835502, 2023). "This suggests that SLAMF8 potentiates the TLR4-NF-κB axis, contributing to an immunosuppressive tumor microenvironment and fostering the conditions for metastatic spread, thereby mechanistically linking this immune checkpoint to aggressive disease." (PMID 41162970, 2025). "These included well-known receptor tyrosine kinase genes (EGFR, TEK and OSMR) that activate MAPK and PI3K signaling pathways, and other tumor-promoter genes (ATP8B2, DAAM1, SLAMF8 and SRGN) as well as tumor-suppressor genes (A2M, DAPK1, RASSF8 and SOCS3)." (PMID 37190308, 2023). "In addition, between tumor tissues and their paired adjacent normal tissues, ARHGAP25, SLAMF8 and OLR1 expression differed significantly." (PMID 38017548, 2023). "In addition, in vitro experiments followed by quantitative real‐time polymerase chain reaction (qRT–PCR) assays showed that SLAMF8 mRNA was mainly expressed on human macrophages and T cells activated by IL‐2 but not on tumor cells." (PMID 34729183, 2021). "Since both SLAMF8 and SLAMF9 lack intracellular signaling motifs, SLAMF9 may also reduce migration by preventing the assembly of the Nox2 complex potentially both in TAM and tumor cells." (PMID 30232321, 2018).
cancer (7 papers, 2021 to 2025). A tumor composed of atypical neoplastic, often pleomorphic cells that invade other tissues. "Other KDs were associated with signal transduction and kinase activity (PRKCA, TAOK1, and ADRBK1), membrane transport (SLC9A3R1), metabolism (PPP1R3B), gene regulation (USF1), and immune responses and cancer (SLAMF8, SRC, and KIAA0100)." (PMID 41402937, 2025). "SLAMF8 functions as a cancer-promoting immune checkpoint and could be targeted for therapy in multiple cancer types." (PMID 41162970, 2025). "The research investigated the correlation between SLAMF8 and various factors including the immune microenvironment, microsatellite instability, immune novel antigen, gene mutation, immune regulatory factors, immune blockade TMB, and immune or molecular subtypes of SLAMF8 in verse cancer types." (PMID 38787377, 2024).
infection (4 papers, 2018 to 2025). The state of being infected such as from the introduction of a foreign agent such as serum, vaccine, antigenic substance or organism. "To evaluate whether SLAMF8 can modulate the expression of TLR4 and SLAMF9 and, therefore, influence the observed phenotype in SLAMF8-deficient mice, we analyzed their expression in pMø by RT-PCR after treatment with IFNγ (100 U/ml for 16 h) and infection with S. typhimurium at different time points." (PMID 35837407, 2022). "We identified the cell surface receptors SLAMF7 and SLAMF8 as key shared players in regulating human plasmacytoid cell response to infection and intracellular bacterial survival." (PMID 40231463, 2025). "Altogether, we establish that human pDCs upregulate the levels of both SLAMF7 and SLAMF8 upon infection with live Salmonella, in a process requiring bacterial viability and prokaryotic RNA recognition." (PMID 40231463, 2025). "We found that in pDCs SLAMF7 and SLAMF8 are coregulated at the protein and mRNA levels in steady state and upon infection or TLR7/8 stimulation." (PMID 40231463, 2025). "Based on antibody availability, we selected five proteins (FCGR3, FCGR1, CD274, ICAM1, SLAMF8) to profile 24 h after infection with pseudotyped HIV-1 by flow cytometry in CD14- CD11cHi HLADR+ DCs from our cultures." (PMID 29378643, 2018). "Hence, SLAMF8-/- mice exhibited significantly greater bactericidal activity and infection control than wt mice." (PMID 35837407, 2022). "Wild-type and SLAMF8-/- mice were injected intraperitoneally (i.p.)with the same amount of Salmonella wt and SseB- bacteria [5 × 104 colony-forming units (CFUs)], and the number of CFUs was evaluated in tissue homogenates 48 h post infection." (PMID 35837407, 2022). "Here, we found that EAT-2 was highly expressed in primary human pDCs, as well as in CAL-1 cells, and stable upon infection with Salmonella and when SLAMF7 or SLAMF8 was downregulated." (PMID 40231463, 2025). "Our results showed that SLAMF8 expression increased in stable COPD patient, which can be used to alleviate inflammatory conditions in patients aggravated by infection." (PMID 35369515, 2022). "Our findings identify human SLAMF7 and SLAMF8 as immunoreceptors that trigger human pDC maturation, activation, and proinflammatory cytokine and type I IFN secretion, and promote as well the survival of intracellular bacteria during infection." (PMID 40231463, 2025).
bacterial infection (2 papers, 2022 to 2025). "Overall, our results unravel essential shared multifaceted roles of SLAMF7 and SLAMF8 in finely tuning human pDC responses to intracellular bacterial infections with potential for future diagnostic and therapeutic applications." (PMID 40231463, 2025). "Collectively, these findings indicate that SLAMF7 and SLAMF8 play a positive regulatory role in human pDC responses to bacterial infection by promoting cell activation and proinflammatory cytokine and IFN type I secretion." (PMID 40231463, 2025). "Therefore, in conclusion, SLAMF8 intervention upon bacterial infection downregulates mouse macrophage activation, and confirmed that SLAMF8 receptor could be a potential therapeutic target for the treatment of severe or unresolved inflammatory conditions." (PMID 35837407, 2022).
infectious disease (1 paper, 2025). A disorder directly resulting from the presence and activity of a microbial, viral, or parasitic agent in humans. "Human blood transcriptomic signatures reveal changes in SLAMF7 and SLAMF8 expression levels in a large panel of infectious diseases." (PMID 40231463, 2025).
SLAMF8 also shares sentences with these, for which no sentence is quoted: Sepsis (2 papers); atherosclerosis (1); GI tumors (1); Heat Stroke (1); Lyme borreliosis (1); multiple myeloma (1); Obesity (1); prostate adenocarcinoma (1); Salmonella gastroenteritis (1); salmonellosis (1); skin sensitization (1); Thrombosis (1).